RPE65 (retinoid isomerohydrolase RPE65)
Diseases named in the same sentence as RPE65 in open-access papers (continued):
Sharing a sentence is not in itself a finding about the gene and the disease.
Retinal dystrophy (continued). "Recent Phase I clinical trials for RPE65 gene replacement therapy provide hopeful prospects for the treatment of inherited retinal dystrophies." (PMID 20683928, 2010). "Whilst the very first FDA approved gene therapy was for RPE65-mediated inherited retinal dystrophy, evolving strategies are making the technology applicable to more genetically heterogenous common conditions such as glaucoma, diabetic retinopathy and age-related macular degeneration." (PMID 39516652, 2025). "We discuss the fundamental principles of gene therapy, including the use of viral and non-viral vectors, and highlight key developments such as the approval of Luxturna for RPE65-mediated retinal dystrophy and the application of gene editing technologies like CRISPR/Cas9." (PMID 39439625, 2024). "It became a prominent outcome measure in RPE65-associted retinal dystrophy clinical trials." (PMID 37762657, 2023). "Our study evaluated the morphological and functional outcomes, and the side effects, of voretigene neparvovec (VN) gene therapy for RPE65-mediated inherited retinal dystrophies (IRDs) in 12 eyes (six patients) at the Oxford Eye Hospital with a mean follow-up duration of 8.2 (range 1–12) months." (PMID 37892166, 2023). "Over the last 10 years, gene therapy for biallelic RPE65-mediated inherited retinal dystrophy has been the subject of many clinical trials, leading to the first United State Food and Drug Administration (US FDA)-approved ocular gene therapy for the treatment of an inherited retinal disorder." (PMID 38983032, 2023). "Approved gene therapies embrace Luxturna to treat RPE65-mediated inherited retinal dystrophy, Glybera to cure familial lipoprotein lipase (LPL) deficiency (LPLD), while Roctavian (BMN 270) promising as therapeutic for hemophilia A, is awaiting approval from the Food and Drug Administration." (PMID 37958989, 2023). "Moreover, patients with RPE65-mediated inherited retinal dystrophy were subjected to AAV2-based RPE65 gene replacement therapy in a phase III study, which provided maximum possible vision improvement." (PMID 36992407, 2023). "The occurrence of mutations in the retinal pigment epithelium-specific 65 kDa protein (RPE65) gene (henceforward, RPE65 mutations) within retinal dystrophies is rare by Swiss standards, and these mutations may cause RP or LCA." (PMID 35765055, 2022). "Moreover, we report visual improvement, including full visual recovery, following gene therapy in severe congenital RPE65-mediated retinal dystrophy." (PMID 36672611, 2022). "In the pivotal Phase III randomized controlled clinical trial, bilateral subretinal voretigene neparvovec-rzyl (Luxturna; AAV2-hRPE65v2; Spark Therapeutics [Philadelphia, PA]/Roche) administration was evaluated for safety and efficacy in patients with RPE65-mediated inherited retinal dystrophy." (PMID 35467460, 2022). "Although neutralizing antibodies to AAV exist, it was shown that second administration of AAV2 vector expressing RPE65 gene into the subretinal space in individuals with inherited retinal dystrophy to the second eye after previous exposure to AAV2 was safe and effective." (PMID 33562561, 2021). "In some cases, however, FA is associated with cone dystrophy, and in fact, the spectrum of RPE65-related phenotypes with white fundus lesions may also include more generalized presentations of retinal dystrophy, resembling the more typical RPE65-related retinal dystrophy." (PMID 41251530, 2025). "Thus, given the recent approval of the drug, one can consider RPE65-mediated IRDs as an example of retinal dystrophy with a definite genetic diagnosis but a highly variable phenotypic presentation in patients carrying this genetic mutation that can manifest itself in different types of IRDs." (PMID 37762059, 2023).
Retinal dystrophy (continued). "The siblings studied here had a severe retinal dystrophy phenotype and review of genotypic findings and segregation studies showed compound heterozygous variants in RPE65, with one classified as a pathogenic variant and the other a novel synonymous VUS, RPE65:c.93A>G p.(Thr31Thr)." (PMID 34938339, 2021). "Hence, Rpe65 knockout mice are a model for studying RPE65-mediated retinal dystrophy." (PMID 28928775, 2017). "Several genes have been shown to be involved in early onset retinal dystrophies, including CRB1 and RPE65." (PMID 32922261, 2020). "Some of these proteins are well-studied in retinal dystrophy, such as CRB1, RP2, RPE65, and PCDH15." (PMID 36139394, 2022). "The presence of a pathogenic variant in the RPE65 gene indicates that she is additionally a carrier of recessively inherited RPE65-related retinal dystrophy, a state that does not qualify her for Luxturna gene therapy." (PMID 34906171, 2021).
retinal degeneration (94 papers, 2007 to 2025). Degeneration of the retina. "This generation of functional data will aid in the diagnosis and treatment of patients with RPE65-associated retinal degeneration." (PMID 39975398, 2025). "In summary, the present study demonstrated the protective role of resveratrol against retinal degeneration induced by excessive TH signaling and Rpe65 deficiency in mice." (PMID 40002341, 2025). "Loss-of-function mutations in RPE65 disrupt the visual cycle, leading to childhood-onset retinal degeneration." (PMID 41010033, 2025). "There is an increasing interest in gene augmentation therapeutic strategies for retinal degeneration patients with biallelic mutations in RPE65, since the approval of Voretigene neparvovec." (PMID 38661530, 2024). "AAV gene therapy for ocular disease has become a reality with the market authorisation of LuxturnaTM for RPE65-linked inherited retinal degenerations and many AAV gene therapies currently undergoing phase III clinical trials." (PMID 36839646, 2023). "Downregulation of rpe65a is associated with retinal degeneration in zebrafish, and loss of RPE65 function leads to blindness in humans." (PMID 35736942, 2022). "RPE65-associated LCA (RPE65-LCA) is an inherited retinal degeneration caused by the mutations of RPE65 gene and gene therapy has been developed to be a promising treatment." (PMID 32059734, 2020). "The rd12 mouse, which has a nonsense mutation in the exon 3 of the Rpe65 gene (R44ter), is another mouse model of retinal degeneration caused by a mutation of the Rpe65 gene." (PMID 31781647, 2019). "The SD-OCT findings of the natural course of retinal degeneration in Rpe65–/– mice have been reported by Tanabu and associates." (PMID 31781647, 2019). "Genetic engineering of zebrafish models with germline knockout or patient-specific knock-ins of RPE65 or CRALBP mutations can provide a platform to study the underlying mechanisms leading to retinal degenerations." (PMID 29696141, 2018). "Over 70 different missense mutations, including a dominant mutation, in RPE65 retinoid isomerase are associated with distinct forms of retinal degeneration; however, the disease mechanisms for most of these mutations have not been studied." (PMID 24849605, 2014). "Homozygous null mutation of Rpe65 (Rpe65tvrm148) results in slow retinal degeneration and disorganized OS discs at P14, as observed in Mfrprd6 mice." (PMID 25357075, 2014). "Pharmacological replacement of 11-cis-retinal has been shown to be highly effective at reconstituting functional visual pigment, increasing ERG responses and reducing the rate of retinal degeneration in animals with Rpe65 or Lrat mutations." (PMID 23857173, 2013). "Analogous to the Lrat deletion, genetic deletion or mutation of the Rpe65 gene produces an intrinsic 11-cis-retinoid deficiency leading to the rapid onset of retinal degeneration and blindness." (PMID 23857173, 2013). "For example, a sequence variant in the RPE65 gene has been shown to determine the susceptibility to light damage in different mouse strains, as well as in mice with inherited retinal degeneration." (PMID 22509098, 2012). "Using the Rpe65R91W/R91W mouse, which carries a mutation in the Rpe65 gene leading to progressive photoreceptor degeneration in both patients and mice, we defined stages of retinal degeneration that still allow cone rescue." (PMID 21304899, 2011). "These concerns were approached using a lentiviral-mediated RPE65 gene transfer into the Rpe65R91W/R91W mice which are homozygous for a mutation encountered in patients suffering from early-onset retinal degeneration." (PMID 21304899, 2011). "Gene replacement therapy by delivering missing genes to the retina by way of injection has been shown to be effective in treating a recessive retinal degeneration lebers congenital amaurosis due to mutations in the RPE65 gene." (PMID 21738619, 2011).
retinal degeneration (continued). "Retinal degeneration in Rpe65−/− mice, showing a null mutation in the gene encoding the retinal pigment epithelium 65-kDa protein (Rpe65), was previously reported to depend on continuous activation of a residual transduction cascade by unliganded opsin." (PMID 19672311, 2009). "The superior rod scotomas observed in the patients may result from a combination of genetic mutations in the RPE65 gene affecting rod function and environmental factors like UV exposure, leading to retinal degeneration in specific areas of the visual field." (PMID 41251530, 2025). "In selected cases, genetic therapy may be a viable option, such as Neparvovec for RPE65-associated retinal degeneration, as well as other new clinical trials investigating the use of innovative approaches." (PMID 39946424, 2025). "Indeed, in the context of the RPE65 mutation, the continued progression of retinal degeneration has been reported in both dogs and affected patients, despite evidence of efficacy after treatment with gene therapy." (PMID 37762059, 2023). "Recent studies have described an additional mutant phenotype that may contribute to retinal degeneration in Usher 1B, related to loss-of-function mutations in the RPE65 gene." (PMID 37762059, 2023). "Therefore, loss-of-function mutations in RPE65 impair the visual cycle, contributing to retinal degeneration." (PMID 35383196, 2022). "Mutations in RPE65 are causative of a large proportion (~11%) of early onset retinal degenerations." (PMID 29696141, 2018). "Mutations in RPE65 result in a disrupted chromophore supply, retinal degeneration, and blindness." (PMID 30242264, 2018). "Furthermore, Rpe65 (0.801 fold, P = 0.0290) is a major player in retinol metabolism, and its loss has been directly linked to retinal degeneration." (PMID 28467791, 2017). "The recent promising results from the first clinical trials for inherited retinal degeneration due to mutations in RPE65 have provided a major breakthrough in the field and have helped cement the use of recombinant adeno-associated viruses (AAV) as the major tool for retinal gene supplementation." (PMID 28943836, 2017). "RPE65-deficient (rpe65-/-) mice display a block in the visual cycle, which leads to an absence of 11-cis-retinal and rhodopsin, with severe impairment of rod photoreceptor function, and eventual retinal degeneration." (PMID 26656277, 2015). "We screened the mutant Pde6brd1 (c.1041C > A) allele, two mutant alleles in the Gnat2 gene, Gnat2 (c.518A>G) and Gnat2Cpfl3 (c.598G>A), and the polymorphism in the Rpe65 gene, RPE65Met450Leu [Rpe65 (c.1348C>A)], that has been previously shown to be a genetic modifier for retinal degeneration." (PMID 25147295, 2015). "Also associated to LCA, null mutations in RPE65 result in retinal degeneration due to the basal constitutive activity associated to opsin, the apoprotein form of the visual pigment, leading to a sustained hyperpolarization of the cell." (PMID 25058152, 2014). "In Mfrprd6 eyes, a significant 1.5- to 2.0-fold decrease was observed among transcripts of genes linked to retinal degeneration, including those involved in visual cycle (Rpe65, Lrat, Rgr), phototransduction (Pde6a, Guca1b, Rgs9), and photoreceptor disc morphogenesis (Rpgrip1 and Fscn2)." (PMID 25357075, 2014). "The cause of this progressive retinal degeneration is still unclear, but possible contributions include an inadequate or declining level of RPE65 expression from the delivered transgene or irreversible photoreceptor injury that cannot be reversed with RPE65 restoration." (PMID 35383196, 2022). "In addition, T4R opsin alone is more toxic than T4R opsin bound to 11cis-retinal as evidenced by the much accelerated course of retinal degeneration observed in double mutant dogs that also carry the RPE65 mutation depriving them from the ability to produce the 11-cis retinal chromophore." (PMID 25695253, 2015).
retinal degeneration (continued). "Our previous work, showing that activation of the Bcl-2-related signaling pathway was associated with retinal degeneration in Rpe65-deficient mice, led us to investigate whether this apoptotic pathway was triggered by light-independent, constitutive activity of the phototransduction cascade." (PMID 19672311, 2009). "There are limited therapeutic options currently for patients with retinal degenerations, with only a single FDA-approved gene therapy to treat a narrow subset of patients with mutations in the RPE65 gene (Luxturna)." (PMID 39932789, 2025). "In contrast, suppression of TH signaling reduced photoreceptor degeneration in mouse models of retinal degeneration, including the LCA model of Rpe65-deficient mice." (PMID 40002341, 2025). "RPE65-associated LCA2 became the first IRD to receive approved gene therapy, but long-term studies have revealed continued retinal degeneration despite initial visual improvements." (PMID 41010033, 2025). "A few studies (NCT01014052, NCT01521793) have tested the effect of supplementing 9-cis-retinyl acetate orally (QLT091001), in patients with LRAT and RPE65-related retinal degeneration." (PMID 33712480, 2022). "Recent advancements in genetic analyses have revealed that mutations in some genes that are expressed in RPE, such as MERTK, RPE65, LRAT, or BEST1, cause retinal degeneration." (PMID 35504937, 2022). "In IRDs, retinal degeneration is caused by mutations in either genes expressed in photoreceptors or genes expressed in the adjacent RPE, as it is the case with mutations in RPE65, MERTK or LRAT." (PMID 30970664, 2019). "At the onset of retinal degeneration, the loss of ERK1/2 led to a specific decrease in the level of RPE65 with the mislocalization of lecithin retinol acyltransferase (LRAT)." (PMID 29038159, 2017). "Mutations in the RPE65 gene cause Leber's congenital amaurosis (LCA), a hereditary retinal degeneration most often transmitted with an autosomal recessive pattern of inheritance." (PMID 26124962, 2015). "We identified a total of nine causal mutations, including six novel variants in RPE65, LCA5, USH2A, CNGB1, FAM161A, CERKL and GUCY2D as the underlying cause of inherited retinal degenerations in 13 of 26 pedigrees." (PMID 26352687, 2015). "In the past, other naturally occurring animal models have enabled the study of the retinal degeneration and the start of the development of new therapies, such as RPE65 gene augmentation therapy in dogs." (PMID 24223178, 2013). "Disorganization and shortening of outer segments are early markers of retinal degeneration in Rpe65−/− retinas." (PMID 19672311, 2009). "The aim of this study was to validate and characterize the NGC expression during retinal degeneration in Rpe65-/- mice." (PMID 19050768, 2008). "In the present work, we showed that NGC, IMPG2, and CD44 mRNA expression was induced during retinal degeneration in Rpe65−/− mice." (PMID 19050768, 2008). "The availability of NGC−/− mice will allow a detailed analysis of the importance of NGC in maintaining the retinal neuronal network during retinal degeneration in Rpe65−/− mice." (PMID 19050768, 2008). "During retinal degeneration in Rpe65−/− mice, NGC expression is induced in the neural retina, but not in the RPE, where NGC is expressed at highest levels." (PMID 19050768, 2008). "The authors noticed an initial decrease of Rpe65 expression in a rodent retinal degeneration model." (PMID 39114482, 2024). "One study used CRISPR–Cas9 to correct a nonsense mutation in the RPE65 gene in a mouse LCA model of type 12 (rd12) retinal degeneration, resulting in homology‐directed repair of RPE65 in mouse retinal pigment epithelial tissues, and achieving therapeutic correction in RPE65 mutations." (PMID 39081515, 2024). "In addition, deletion of retinal pigment epithelial extracellular signal-regulated kinase 1/2 leads to reduced RPE65 and retinal degeneration." (PMID 37183261, 2023).